CCR1 (C-C motif chemokine receptor 1)
Diseases named in the same sentence as CCR1 in open-access papers (continued):
Sharing a sentence is not in itself a finding about the gene and the disease.
diabetic neuropathy (3 papers, 2018 to 2023). A chronic, pathological complication associated with diabetes mellitus, where nerve damages are incurred due to diabetic microvascular injury involving small blood vessels that supply these nerves, resulting in peripheral and/or autonomic nerve dysfunction. "In our research, we have shown that a CCR1 antagonist improves the analgesic properties of morphine, which is in agreement with results obtained in mice with diabetic neuropathy and in rats in a CCI model." (PMID 37190544, 2023). "The results of our study in an STZ-induced diabetic neuropathy model show that single intrathecal administration of the CCR1 antagonist J113863 dose-dependently diminished pain-related behavior in STZ-injected mice." (PMID 29593735, 2018). "Moreover, our results suggest the pharmacological blockade of CCR1 in conjunction with morphine administration as a novel therapeutic approach for diabetic neuropathy." (PMID 29593735, 2018). "Additionally, CCR1 antagonists may have decreased pain-like behaviors in a murine model of diabetic neuropathy." (PMID 36611891, 2022). "Both neutralizing antibodies, as well as the CCR1 antagonist, enhanced the effectiveness of morphine in STZ-induced diabetic neuropathy." (PMID 29593735, 2018). "Therefore, we did not observe an increased level of CCR1, which as suggested by our pharmacological experiments, is strongly involved in nociceptive transmission and plays a crucial role in diabetic neuropathy." (PMID 29593735, 2018).
eosinophilia (3 papers, 2021 to 2025). "CCL5 regulates a variety of immune cells, including the transport of T cells, monocytes, eosinophilia, etc., which can bind to at least four receptors, including CCR1, CCR3, CCR5 and GPR75, among which CCR5 is the main receptor of CCL5 in adipose tissue." (PMID 40725440, 2025). "We hypothesized that the interaction between mCCL6 and CCR1 contributes to eosinophilia and allergic inflammation." (PMID 33640900, 2021).
fungal infection (3 papers, 2017 to 2024). "For example, the neutrophil chemokine receptor Ccr1 amplifies late renal immunopathology and increases mortality in mouse systemic fungal infections by mediating the excessive recruitment of neutrophils from the blood to target organs." (PMID 38166150, 2024). "CCR1 knockout mice presented higher mortality, compared to the wild type, when infected with A. fumigatus which suggests a role in the control of fungal infections." (PMID 28797245, 2017). "Compared to TNF-α and IL-10, CCL3/MIP-1⍺ plays an important role in recruiting various cells such as monocytes, macrophages, lymphocytes, and eosinophils via the CCR1 or CCR5 receptor, thereby strengthening the immune response against a fungal infection." (PMID 38967888, 2024).
Hypertension (3 papers, 2022 to 2024). The presence of chronic increased pressure in the systemic arterial system. "However, during hypertension onset at 10 weeks and robust hypertension at 16 weeks, the inflammatory markers Tnf, Il1b, Ccr1, Ccr5, Ilrn, and Ltb4r are statistically significantly upregulated in the kidney of female SHR vs WKY control." (PMID 39514592, 2024).
lung adenocarcinoma (3 papers, 2015 to 2025). A carcinoma that arises from the lung and is characterized by the presence of malignant glandular epithelial cells. "Furthermore, the in vivo targeting of IMCs by the CCR1 inhibitor effectively suppressed tumour progression in vivo (Fig4) in a similar way to the targeting of TAMs in the oncogenic KRAS-induced lung adenocarcinoma model." (PMID 26183450, 2015).
lupus nephritis (3 papers, 2022 to 2025). Glomerulonephritis in the context of systemic lupus erythematosus. "Inhibition of CCR1 can improve the progression of New Zealand black/white (NZB/W) mouse lupus nephritis." (PMID 35935949, 2022). "Similarly, CCR1 blockade reduced renal infiltration of T cells and mononuclear phagocytes in lupus nephritis." (PMID 41343465, 2025). "CCR1 is a member of the β-chemokine receptor family and can interact with numerous ligands, such as CCL5, and suppressing CCR1 could improve lupus nephritis progression in New Zealand black/white mice." (PMID 37313407, 2023).
mastitis (3 papers, 2016 to 2021). Inflammation of breast tissue during lactation or postpartum due to an obstructed duct or infection. "The proteins crucial for acute mastitis (IL-18, Il-1β, TNFα, CCL2, CCR1) demonstrate low expression." (PMID 34663465, 2021).
myocarditis (3 papers, 2015 to 2020). Myocarditis is a condition that is characterized by inflammation of the heart muscle (myocardium). "Our previous data support that the formation of CD8-enriched chagasic myocarditis involves CCR1/CCR5-mediated cell migration." (PMID 25789471, 2015). "However, CC-chemokines acting on their receptors CCR1/CCR5 have been involved in myocarditis formation and cardiomyocyte lesion in acute and chronic T. cruzi infection." (PMID 32194558, 2020). "To shed light on the contribution of CCL5 and its receptors CCR1 and CCR5 in Chagas heart disease, we used a model of CCC that presents fibrosis, CD8-enriched myocarditis, myocardial injury and electrical and functional abnormalities." (PMID 29696014, 2018). "The beneficial effects of Met-RANTES, a partial antagonist of CCR1/CCR5-mediated interactions, have supported the participation of CC-chemokine ligands and receptors in cell migration, myocarditis formation, and heart tissue damage in experimental models of CCC." (PMID 29696014, 2018).
osteoporosis (3 papers, 2014 to 2022). A condition of reduced bone mass, with decreased cortical thickness and a decrease in the number and size of the trabeculae of cancellous bone (but normal chemical composition), resulting in increased fracture incidence. "A 5-gene combination (CCR1, CD33, HCK, LILRB2 and CYBB) was established as an optimal and effective biomarker for osteoporosis using SVM with feature selection and classification procedures." (PMID 34622712, 2021).
Salmonella Infections (3 papers, 2012 to 2014). Infections with bacteria of the genus SALMONELLA. "Polymorphism in the CCR1 region is associated with coeliac disease in humans and Salmonella infection in pig." (PMID 25144185, 2014).
abscess (2 papers, 2012 to 2015). An inflammatory process characterized by the accumulation of pus within a newly formed tissue cavity which is the result of a bacterial, fungal, or parasitic infection or the presence of a foreign body. "Of the host genes tested, we found that transcripts encoding IL-8, IL1β, oncostatin M-like, CCR1, CXCR1 (IL8RA), CCL4 (MIP-1β) and CCL3 (MIP1α)-like proteins were among the most highly up-regulated transcripts during S. aureus abscess formation." (PMID 25719526, 2015).
adenoma (2 papers, 2017 to 2019). A neoplasm arising from the epithelium. "Moreover, CCL9/CCR1 signaling has been shown to recruit myeloid progenitors to tumor area, leading to progression of adenomas to carcinomas and also enhancing tumor invasion." (PMID 31649887, 2019).
anemia (2 papers, 2024). A reduction in the number of red blood cells, the amount of hemoglobin, and/or the volume of packed red blood cells. "The suppressive effect of CCL3 on erythropoiesis can be blocked by CCR1 antagonists, suggesting that CCL3/CCR1/phos-p38 is critical to CCL3-induced anemia in MM." (PMID 38475811, 2024).
breast invasive ductal carcinoma (2 papers, 2017 to 2023). "CCR1 was highly expressed in human breast invasive ductal carcinoma (IDC) compared to adjacent normal tissues." (PMID 29212252, 2017).
Burkitt lymphoma (2 papers, 2022 to 2025). A rare form of malignant mature B-cell non-Hodgkin lymphoma. "Previous work showed that LMP1 can induce CCL4 release and that CCR1 surface expression in EBV-positive Burkitt’s lymphomas requires full latent gene expression." (PMID 40389409, 2025). "We confirm that CCR1 and CCL4 expression in Burkitt’s lymphoma cells requires full latent gene expression." (PMID 40389409, 2025). "To establish whether these viral genes control CCL4 and CCR1 expression in infected B cells, we first monitored their expression in an early and a late passage of the MUTU Burkitt’s lymphoma cell line." (PMID 40389409, 2025).
coeliac disease (2 papers, 2014 to 2015). "Forty eight of our DE genes belong to this pathway, including 4 genes that have been genetically linked to coeliac disease: CCR1, IL18RAP, IL21 and IL2RA." (PMID 26444573, 2015).
dengue (2 papers, 2010 to 2019). "In the present work we have investigated the putative role of CC chemokine receptors CCR1, CCR2 and CCR4 in the context of experimental Dengue virus infection." (PMID 21206747, 2010). "Due to its various binding receptors such as CCR1, CCR2 and CCR5, CCL8/MCP-2 may have independent effects on immune response to dengue virus infection by engaging with different receptors to activate or suppress the effect of other chemokines." (PMID 30744623, 2019). "Our major findings can be summarized as follows: 1) CCR1 does not seem to have a major role in the pathogenesis of severe experimental dengue infection; 2) CCR2 appeared to contribute to dengue-associated liver damage and this was reflected on decreased leukocyte activation and decreased lethality." (PMID 21206747, 2010).
endothelial dysfunction (2 papers, 2019 to 2023). In vascular diseases, endothelial dysfunction is a systemic pathological state of the endothelium (the inner lining of blood vessels) and can be broadly defined as an imbalance between vasodilating and vasoconstricting substances produced by (or acting on) the endothelium. "The presence of some endothelial dysfunction in this model is consistent with the IBD-related increase in expression of the chemokine ccl5 and its receptor ccr1, which are linked to endothelial dysfunction and leukocyte transmigration into arteries." (PMID 37342800, 2023). "Prevention of endothelial dysfunction by TNTL may be mediated by the inhibition of MIP1γ/CCR1 axis." (PMID 31331327, 2019).
experimental autoimmune encephalomyelitis (2 papers, 2007 to 2025). An autoimmune demyelinating disease of the central nervous system that is produced experimentally in animals by the injection of homogenized brain or spinal cord in Freund's adjuvant. "In this study, we characterize the regional, temporal and cellular expression of CCR1, CCR2 and CCR5 mRNA in the spinal cord of rats with myelin oligodendrocyte glycoprotein-induced experimental autoimmune encephalomyelitis (MOG-EAE)." (PMID 17484785, 2007).
glioblastoma (2 papers, 2021 to 2023). The most malignant astrocytic tumor (WHO grade IV). "A mouse glioblastoma study showed that CCL8, primarily secreted by TAMs, helps in the formation of pseudopodia-like structures in glioblastoma cells via C-C motif chemokine receptor (CCR) 1 (CCR1) or CCR5 axes, which promotes tumor migration and invasion." (PMID 34503065, 2021).
glomerulonephritis (2 papers, 2021 to 2022). A renal disorder characterized by damage in the glomeruli. "Similar to our findings, increased expression of RANTES, a ligand for the chemokine receptors CCR1, CCR3, and CCR5, has been observed in vivo in various inflammatory diseases, including adjuvant-induced arthritis, glomerulonephritis, granulomatous inflammation, and OP." (PMID 35270014, 2022).
Granuloma (2 papers, 2011 to 2025). A compact, organized collection of mature mononuclear phagocytes, which may be but is not necessarily accompanied by accessory features such as necrosis. "Overall this study suggests that CCL2 and CCL5 may be interacting with mononuclear cells expressing specific CC chemokines receptors (CCL2 → CCR2, CCL5 → CCR1, CCR3, and CCR5) and are important biologically in the formation of pulmonary sarcoidosis granulomas." (PMID 21463523, 2011). "We found that epithelioid histocytes, macrophages and infiltrating lymphocytes that form the pulmonary sarcoid non-necrotizing granuloma were all expressing CCR1 and CCR3." (PMID 21463523, 2011).
Hepatitis (2 papers, 2019 to 2022). Inflammation of the liver. "The sequential requirement for CXCR3 and CCR1 for the mobilization of splenic NK cells and their subsequent accumulation in the liver was demonstrated in a murine Con A-induced hepatitis model." (PMID 31704965, 2019).
Insulin resistance (2 papers, 2019 to 2022). Increased resistance towards insulin, that is, diminished effectiveness of insulin in reducing blood glucose levels. "Tregs are abundant in the lean adipose tissue of mice, but their number was significantly lower in the insulin resistance animal model due to decreased CCR1, CCR2, and CXCR6 expression, which might be responsible for the Treg-specific accumulation." (PMID 31297120, 2019).
intracerebral hemorrhage (2 papers, 2022 to 2023). A cerebrovascular disorder characterized by bleeding into one or both cerebral hemispheres including the basal ganglia and the cerebral cortex. "Suppression of CCR1 activation by the CCR1/TPR1/ERK1/2 signaling pathway in an intracerebral hemorrhage mouse model can attenuate neuroinflammation, hence decreasing brain edema and improving cognitive functions." (PMID 36875640, 2023). "However, much remains unknown regarding CCL5/CCR1 signaling in blood–brain barrier (BBB) permeability after intracerebral hemorrhage (ICH)." (PMID 35062973, 2022).
ischaemic stroke (2 papers, 2021 to 2025). "CCR1 is a chemokine receptor involved in inflammatory responses, and its activation can contribute to vascular inflammation, a known risk factor for ischemic stroke." (PMID 40624693, 2025). "Previously, we identified the human orthologues for a number of rat genes, which expression was changed after ischaemic stroke (Adora2a, Bcl3, Ccl22, Ccr1, Cd14, Gpr6, Gpr88, Rgs9, and other genes)." (PMID 34946819, 2021). "In ischemic stroke, we found that MPO, CALCRL, PPP5C, KTN1-AS1, CCR1, CTB-50L17.9, CCR9, ZNF362, ZIK1, ELP5, CKAP2, NUP88, and SEC16A show risk effects (OR > 1)." (PMID 40624693, 2025).
kidney damage (2 papers, 2022 to 2025). "Given that these pathways are central to M1 macrophage activation, we propose that in BMDMs, CCL5 activates MAPK and NF-κB signaling via CCR1 and CCR5, leading to sustained M1 polarization and kidney damage." (PMID 40986444, 2025). "A chemical blockade of CCR1 reduces inflammation and interstitial fibrosis in CKD murine models, such as adriamycin-induced nephropathy and UUO." (PMID 35806457, 2022).
liver cirrhosis (2 papers, 2010 to 2017). "Interestingly, when we re-conducted the GO analysis on overlapping DE genes in liver cirrhosis and HCC (e.g., CCR1, CXCL6, and CXCL12), the results showed that these genes were mainly enriched in the same immune response terms (especially “T cell immune process”)." (PMID 28355233, 2017).
lung adenoma (2 papers, 2015 to 2022). A benign, well circumscribed epithelial neoplasm that arises from the bronchus or the lung parenchyma. "We have previously shown that autocrine CC chemokine receptor 1 (CCR1) signalling plays a critical role in IMC accumulation in the BRAFV600E-driven lung adenoma model." (PMID 34779486, 2022). "In this model, we have found that immature macrophage-lineage cells (IMCs) producing PDGFA, TGFβ and CC chemokines are recruited to the stroma of premalignant lung adenomas through CC chemokine receptor 1 (CCR1)-dependent mechanisms." (PMID 26183450, 2015). "We show here that immature macrophage-lineage cells (IMCs) are recruited to the stroma of senescent lung adenomas through CCR1-dependent mechanisms." (PMID 26183450, 2015).
nasal polyps (2 papers, 2022 to 2024). "CCR1 is also reported as a M2 macrophage-related gene in chronic rhinosinusitis with nasal polyps." (PMID 39351239, 2024).
peripheral nerve injury (2 papers, 2017 to 2022). Injury to a peripheral nerve. "After SCI, Ccl3 were induced significantly in the dorsal horns 2 days after lesion and remained at high levels with significantly higher intensities, while, after peripheral nerve injury, Ccl3 and their receptors (CCR2 and CCR1/CCR5, resp)." (PMID 29164149, 2017). "Our research is the first comprehensive behavioral and biochemical study showing that many endogenous ligands of CCR1 (CCL2/3/5/7/8/9) and CCR3 (CCL5/7/8) are significant in the development (CCL2/3/5/7/8/9) and maintenance (CCL2/7/8) of neuropathic pain after peripheral nerve injury in mice." (PMID 36611891, 2022).
sarcoidosis (2 papers, 2015 to 2020). Sarcoidosis is a multisystemic disorder of unknown cause characterized by the formation of immune granulomas in involved organs. "For example, here, among other genes, STAT1, IL10RA, and PTEN were underexpressed in sarcoidosis CD14 monocytes compared to controls while CXCR4, ATG12, HIF1A, CCR1, and IER3 were overexpressed, consistent with the effects of TGFB1 signaling." (PMID 33363531, 2020).
sarcoma (2 papers, 2007 to 2019). A usually aggressive malignant neoplasm of the soft tissue or bone. "A recent study showed that CCL16 stimulated cell migration of human osteogenic sarcoma cells expressing CCR1." (PMID 17506907, 2007).
sarcopenia (2 papers, 2025 to 2026). Progressive decline in muscle mass due to aging which results in decreased functional capacity of muscles. "Upon confirming that the overexpression of CCL5 can induce sarcopenia in skeletal muscle, we analyzed the ccr5 and ccr1 gene expression." (PMID 39857418, 2025).
triple-negative breast carcinoma (2 papers, 2017 to 2023). An invasive breast carcinoma which is negative for expression of estrogen receptor (ER), progesterone receptor (PR), and human epidermal growth factor receptor 2 (HER2). "The close contact between ASCs and triple-negative breast carcinoma cells in the 3D environment appeared to be a distinct stimulus that specifically up-regulated CCR1 expression." (PMID 37444610, 2023). "Migration assays were performed to analyze the functional relevance of the CCL5/CCR1 axis and revealed a migration-promoting role of this specific interaction in triple-negative breast cancer cells." (PMID 37444610, 2023). "Altogether, these data strongly indicate a possible role of CCR1 in the migration ability of triple-negative breast cancer cells in an adipose microenvironment." (PMID 37444610, 2023). "It will be of great interest to determine whether targeting of AKT-mTOR-STAT3 axis-dependent CCR1 expression can be a potential therapeutic strategy for the management of triple-negative breast cancer." (PMID 29212252, 2017).
abortion (1 paper, 2025). the ending of pregnancy by removing a fetus or embryo before it can survive outside the uterus. "Immune pathways were also among the top ones, with several immune genes downregulated in abortion tissues, including Il1b, Ccr1 and Ccr1/1, but also genes expressed in ILC and uNK cells, such as Prf1, Gzmb, Gzmd and Gzme." (PMID 40658772, 2025).
acute GVHD (1 paper, 2024). "In xenograft mouse model, CCR1 mRNA was upregulated in the liver and intestines suggesting that CCR1 may play a vital role in the pathogenesis of acute GVHD." (PMID 39840040, 2024).
allergic contact dermatitis (1 paper, 2022). An inflammatory skin condition caused by an immune response to direct contact between the skin and an allergen. "It is believed that in the case of allergic contact dermatitis, more than one chemokine should be targeted as multiple members of the chemokine network are involved, and cannot be sufficiently modulated via CCR1 monotherapy." (PMID 35399952, 2022).
angina (1 paper, 2013). "The expressed mRNA levels of CCR1 and CXCR4 were higher in PBMCs from UA patients, comparing both stable angina ones and control subjects." (PMID 23762142, 2013).
atopic dermatitis (1 paper, 2024). "However, acknowledging the ongoing importance of LC in atopic dermatitis, additional research is needed to elucidate how significant genetic factors (Trp73, Orm-1, Chi3l3, Ccl20, AnXa1, Alox5, Ccr1, and Fcεr1a, etc.)identified in our study may interact with LC function and the disease process." (PMID 38834629, 2024).